HIPK1 (homeodomain interacting protein kinase 1)
Description:
Serine/threonine-protein kinase involved in transcription regulation and TNF-mediated cellular apoptosis. Plays a role as a corepressor for homeodomain transcription factors. Phosphorylates DAXX and MYB. Phosphorylates DAXX in response to stress, and mediates its translocation from the nucleus to the cytoplasm. Inactivates MYB transcription factor activity by phosphorylation. Prevents MAP3K5-JNK activation in the absence of TNF. TNF triggers its translocation to the cytoplasm in response to stress stimuli, thus activating nuclear MAP3K5-JNK by derepression and promoting apoptosis. May be involved in anti-oxidative stress responses. Involved in the regulation of eye size, lens formation and retinal lamination during late embryogenesis. Promotes angiogenesis and to be involved in erythroid differentiation. May be involved in malignant squamous cell tumor formation. Phosphorylates PAGE4 at 'Thr-51' which is critical for the ability of PAGE4 to potentiate the transcriptional activator activity of JUN.
Synonyms: KIAA0630; MYAK; NBAK2; MGC26642; MGC33446; MGC33548
Tractability: Small molecule: a high-quality ligand is known; it belongs to a druggable protein family. PROTAC: it is named in the literature on targeted protein degradation; UniProt records ubiquitination sites on it; ubiquitination databases record sites on it; a small molecule that binds it is known.
Target class: CMGC protein kinase group; CMGC protein kinase HIPK subfamily; Enzyme; Kinase; CMGC protein kinase DYRK family; Protein Kinase
Gene: Protein-coding gene on chromosome 1 (113,929,324 to 113,977,869, forward strand). Ensembl gene ENSG00000163349.
Subcellular location: Nucleus; Cytoplasm; Nucleus speckle
Subcellular location (Human Protein Atlas): Basal body; Cytosol; Nucleoplasm; Centrosome
Pathways (Reactome):
Gene expression (Transcription): YAP1- and WWTR1 (TAZ)-stimulated gene expression
Muscle contraction: Physiological factors
Gene Ontology:
Molecular function: protein binding; ATP binding; protein kinase activity; protein serine kinase activity; protein serine/threonine kinase activity
Biological process: endothelial cell apoptotic process; extrinsic apoptotic signaling pathway; protein phosphorylation; regulation of tumor necrosis factor-mediated signaling pathway; definitive hemopoiesis; eye development; positive regulation of angiogenesis; smoothened signaling pathway; adherens junction assembly; embryonic camera-type eye morphogenesis; embryonic retina morphogenesis in camera-type eye; iris morphogenesis; lens induction in camera-type eye; neuron differentiation; retina layer formation
Cellular component: cytoplasm; cytosol; nuclear speck; nucleoplasm; nucleus; PML body
Genetic constraint (gnomAD): Loss-of-function variants: 28 observed, 107.96 expected, observed/expected ratio (o/e) 0.26, 90% interval 0.19 to 0.36. The upper end of that interval is the gene's LOEUF score, 0.36, which puts it in group 1 of 6, group 1 being the genes least tolerant of losing a copy. Missense variants: 1,100 observed, 1,477.6 expected, observed/expected ratio (o/e) 0.74, 90% interval 0.71 to 0.78. Synonymous variants: 588 observed, 569.89 expected, observed/expected ratio (o/e) 1.03, 90% interval 0.96 to 1.11.
Homologues: Orthologues: chimpanzee HIPK1 (99% identical), pig HIPK1 (99% identical), dog HIPK1 (98% identical), guinea pig HIPK1 (98% identical), mouse Hipk1 (98% identical), rat Hipk1 (97% identical), rabbit HIPK1 (89% identical), macaque HIPK1 (88% identical), tropical clawed frog hipk1 (84% identical), zebrafish hipk1a (52% identical), zebrafish hipk1b (50% identical), Drosophila melanogaster mnb (13% identical), and 3 more. Paralogues in human: HIPK2 (64% identical), HIPK3 (48% identical), HIPK4 (19% identical), DYRK1A (14% identical), DYRK2 (13% identical), DYRK1B (13% identical), DYRK4 (12% identical), DYRK3 (12% identical), CLK1 (10% identical), CLK2 (10% identical), CLK3 (9% identical), CLK4 (9% identical).
Diseases named in the same sentence as HIPK1 in open-access papers:
HIPK1 is named in the same sentence as 29 diseases in open-access papers, as found by Europe PMC text mining. Sharing a sentence is not in itself a finding about the gene and the disease. The quoted sentences say what the papers report.
breast carcinoma (4 papers, 2020 to 2021). "It has been reported that HIPK1 stimulates the epithelial–mesenchymal transition (EMT) in breast cancer cells via activation of the Wnt/β-catenin pathway." (PMID 34723781, 2021). "For instance, miR-200c/141 targets to HIPK1/β-catenin axis to regulate the heterogeneity of breast cancer stem cells." (PMID 33318478, 2020). "In fact, MiR-200c regulates EMT by inhibiting ZEB1 and ZEB2 expression in breast cancer cells, while it regulates CSCs heterogeneity via targeting the HIPK1/β-Catenin axis." (PMID 33092068, 2020). "Previous studies have suggested that HIPK1 is a carcinogenic gene controlling cell apoptosis and DNA damage repair, and can stimulate EMT in breast cancer cells via activation of Wnt/β-catenin pathway, but HIPK1 has been little explored in LC." (PMID 34723781, 2021).
prostate carcinoma (3 papers, 2014 to 2023). A carcinoma that arises from epithelial cells of the prostate gland. "HIPK1 treatment resulted in increased c-Jun dependent transcription activity in cell models of prostate cancer while CLK2 phosphorylation caused the opposite." (PMID 36671509, 2023). "Importantly, HIPK1 is expressed in both androgen-dependent and androgen-independent prostate cancer cells, whereas CLK2 and PAGE4 are expressed only in androgen-dependent cells." (PMID 30909517, 2019). "Phosphorylation by HIPK1 effectively disrupts the PAGE4 interaction with c-Jun and consequently stimulated c-Jun dependent transcription in prostate cancer cell models." (PMID 30909517, 2019).
colon cancer (2 papers, 2019 to 2020). "Additionally, miR-770-5p targeted HIPK1 to regulate the resistance of colon cancer to methotrexate." (PMID 32309847, 2020).
hypertrophic cardiomyopathy (2 papers, 2023 to 2025). A condition in which the myocardium is hypertrophied without an obvious cause. "In the current study, we observed that HIPK1 was increased in animal and cellular experimental models of pathological cardiac hypertrophy and also increased in human hypertrophic cardiomyopathy, which prompted us to further examine its functional role and molecular mechanisms." (PMID 37098980, 2023). "Importantly, we collected human cardiac tissues from patients with hypertrophic cardiomyopathy (HCM) and control samples, and observed a marked upregulation of HIPK1 in HCM group, indicating that HIPK1 was also upregulated in the hypertrophic myocardium in humans." (PMID 37098980, 2023).
lung carcinoma (2 papers, 2021 to 2024). "In lung cancer, miR-889-3p inhibits cell proliferation and EMT by downregulating homeodomain interacting protein kinase 1 (HIPK1)." (PMID 38570856, 2024).
acute kidney injury (1 paper, 2021). Sudden and sustained deterioration of the kidney function characterized by decreased glomerular filtration rate, increased serum creatinine or oliguria. "a study has testified that HIPK1, as a target gene of miR-495-3p, takes part in the modulation of the development of acute kidney injury." (PMID 34709114, 2021).
cardiac hypertrophy (1 paper, 2023). "Inhibition of the CREB‐C/EBPβ axis is the molecular basis mediating the myocardial protective effect of reducing HIPK1 against pathological cardiac hypertrophy." (PMID 37098980, 2023). "Collectively, our data identify a novel and important role of HIPK1 in pathological cardiac hypertrophy and suggest that targeting HIPK1 is a promising therapeutic strategy to attenuate pathological cardiac hypertrophy and heart failure." (PMID 37098980, 2023). "After delineating the function and molecular mechanism of HIPK1, we decided to explore the effect of HIPK1 reduction on pathological cardiac hypertrophy via a gene therapy approach." (PMID 37098980, 2023). "Collectively, these data consistently demonstrate that HIPK1 is upregulated during pathological myocardial hypertrophy process." (PMID 37098980, 2023). "Collectively, these data for the first time reveal that reducing HIPK1 has an antihypertrophic effect against pathological cardiac hypertrophy." (PMID 37098980, 2023). "In summary, our data describe the antihypertrophic effect of HIPK1 inhibition in pathological cardiac hypertrophy." (PMID 37098980, 2023). "To dissect the functional role of HIPK1 in pathological cardiac hypertrophy in vivo, we subjected HIPK1 KO (Line‐1) mice to TAC model." (PMID 37098980, 2023). "HIPK1 inhibition prevents pathological cardiac hypertrophy through inhibiting the cAMP response element binding protein (CREB) phosphorylation at Ser271 and inactivating CCAAT/enhancer‐binding protein β (C/EBPβ)." (PMID 37098980, 2023). "Collectively, these data provide in vivo evidence that CREB inhibition is essential to mediate the beneficial effect of targeting HIPK1 in preventing pathological cardiac hypertrophy." (PMID 37098980, 2023). "TAC‐induced myocardial hypertrophy and cardiac fibrosis were also attenuated upon HIPK1 knockdown, accompanied with reduced expression of pathological hypertrophy marker genes (ANP, BNP, and β‐MHC) and fibrosis‐associated genes (Col1a1, Col3a1, and CTGF)." (PMID 37098980, 2023). "Collectively, these findings indicate that targeting HIPK1 can prevent pathological cardiac hypertrophy at least partly through inhibition of the CREB‐C/EBPβ axis." (PMID 37098980, 2023). "This is the first study to demonstrate that HIPK1 contributes to pathological cardiac hypertrophy, and that downregulating HIPK1 is beneficial to attenuate pathological hypertrophy, cardiac remodeling, and heart failure." (PMID 37098980, 2023). "In the experimental TAC model, HIPK1 KO mice manifested markedly reduced pathological myocardial hypertrophy and developed less interstitial fibrotic changes after TAC injury." (PMID 37098980, 2023). "In the present study, we first observed that HIPK1 was upregulated in cardiomyocytes during the hypertrophic process of TAC‐induced cardiac hypertrophy, and was consistently upregulated in the cellular model of hypertrophic cardiomyocytes upon PE stress." (PMID 37098980, 2023). "Collectively, genetic HIPK1 removal attenuates TAC‐induced pathological cardiac hypertrophy and cardiac dysfunction." (PMID 37098980, 2023). "Our study also reveals that reducing HIPK1 can prevent pathological cardiac hypertrophy through inhibition of the CREB‐C/EBPβ axis." (PMID 37098980, 2023). "We then examined the development of pathological cardiac hypertrophy using genetic HIPK1 ablation mice." (PMID 37098980, 2023). "In conclusion, HIPK1 inhibition may serve as a promising novel therapeutic strategy to attenuate pathological cardiac hypertrophy and heart failure." (PMID 37098980, 2023). "Here, it is observed that HIPK1 is increased during pathological cardiac hypertrophy." (PMID 37098980, 2023). "In turn, CREB inhibition might also downregulate HIPK1 at transcriptional level, thus forming a beneficial regulation loop in protecting against pathological cardiac hypertrophy." (PMID 37098980, 2023).
cardiac hypertrophy (continued). "We also observed that HIPK1 hetero‐knockout mice were resistant to pathological cardiac hypertrophy, further supporting that reducing HIPK1 is sufficient to prevent pathological cardiac hypertrophy." (PMID 37098980, 2023). "To assess whether the CREB‐C/EBPβ axis contributes to the functional role of HIPK1 in pathological cardiac hypertrophy, we co‐treated NRCMs with sh‐HIPK1 and OE‐CREB (or OE‐C/EBPβ) vectors upon PE stress." (PMID 37098980, 2023). "Thus, both genetic ablation and gene therapy targeting HIPK1 exert notable beneficial effects against pathological cardiac hypertrophy via inhibition of the CREB‐C/EBPβ axis." (PMID 37098980, 2023). "Furthermore, we demonstrate that gene therapy using AAV9‐mediated HIPK1 knockdown is protective against pathological cardiac hypertrophy through inhibiting CREB and that inhibition of HIPK1 and CREB forms a synergistic pathway in preventing pathological cardiac hypertrophy." (PMID 37098980, 2023). "Using another HIPK1 KO mice line (Line‐2), we confirmed these results having improved cardiac function and reduced myocardial hypertrophy and cardiac fibrosis after TAC surgery in HIPK1 KO mice." (PMID 37098980, 2023). "Inhibition of HIPK1 and CREB forms a synergistic pathway in preventing pathological cardiac hypertrophy." (PMID 37098980, 2023). "Our findings propose that targeting HIPK1 and subsequently inhibiting the CREB‐C/EBPβ axis may provide a novel therapeutic approach for pathological cardiac hypertrophy and heart failure." (PMID 37098980, 2023). "Last but not at least, CREB was found to positively regulate HIPK1 expression both in heart tissues in vivo and in cardiomyocytes in vitro, suggesting that inhibition of HIPK1 and CREB can form a synergistic pathway in preventing pathological cardiac hypertrophy." (PMID 37098980, 2023). "We treated mice via tail vein injections of AAV9 that mediated HIPK1 knockdown driven by a cardiac‐specific troponin promoter (cTnT‐shHIPK1‐AAV9) or control AAV9 vectors (cTnT‐CTL‐AAV9) and subsequently followed 1 week later by TAC surgery to induce pathological cardiac hypertrophy." (PMID 37098980, 2023).
colon adenocarcinoma (1 paper, 2025). "In colon adenocarcinoma, miR-770-5p downregulates HIPK1 to modulate methotrexate resistance." (PMID 40176914, 2025).
Crohn disease (1 paper, 2022). A gastrointestinal disorder characterized by chronic inflammation involving all layers of the intestinal wall, noncaseating granulomas affecting the intestinal wall and regional lymph nodes, and transmural fibrosis. "Within human studies, the HIPK1 gene is associated with chronic inflammatory diseases such as Crohn’s disease, primary sclerosing cholangitis, and ulcerative colitis, all of which localize to the gastrointestinal tract." (PMID 36553445, 2022).
heart failure (1 paper, 2023). Inability of the heart to pump blood at an adequate rate to meet tissue metabolic requirements. "Both genetic ablation and gene therapy targeting HIPK1 are protective against pathological hypertrophy and heart failure in vivo." (PMID 37098980, 2023).
invasive breast carcinoma (1 paper, 2023). A carcinoma that infiltrates the breast parenchyma. "Some highly phosphorylated phosphosites, which have not been shown to be associated with HER2 protein expression, include homeodomain-interacting protein kinase 1 (HIPK1), which is highly expressed in invasive breast cancers." (PMID 36661191, 2023).
Kidney Clear Cell Carcinoma (1 paper, 2021). "Among the 4 HIPKs, HIPK1 and HIPK3 mRNA expression was downregulated in cancer tissues from The Cancer Genome Atlas Kidney Clear Cell Carcinoma (TCGA-KIRC) database." (PMID 33495417, 2021).
melanoma (1 paper, 2021). A malignant, usually aggressive tumor composed of atypical, neoplastic melanocytes. "In addition, miR-3065-5p functions as an antitumor miRNA to inhibit the proliferation of melanoma cells by targeting the HIPK1 and ITGA1 genes." (PMID 34656128, 2021).
osteoporosis (1 paper, 2023). A condition of reduced bone mass, with decreased cortical thickness and a decrease in the number and size of the trabeculae of cancellous bone (but normal chemical composition), resulting in increased fracture incidence. "Since patients with type 2 diabetes had impaired metabolism and a higher prevalence of osteoporosis in postmenopausal women, whether the low expression of HIPK1 impairs the body’s overall metabolic capacity and leads to PMOP needs to be further investigated and validated." (PMID 37683138, 2023).
pancreatic cancer (1 paper, 2014). "They included proteins that are known to be up-regulated in pancreatic cancer (e.g. Mucin-1), but the majority were new candidate markers such as HIPK1 & MLCK." (PMID 24670416, 2014).
tumor (9 papers, 2015 to 2025). "Down-regulation of miR-141 promotes EMT-like BC stem cells by directly up-regulating HIPK1, which results in tumor metastasis and deregulation of Wnt/β-catenin pathway." (PMID 36418345, 2022). "It was found in this study that HIPK1 was up-regulated in tumor tissues of LC patients, and the depletion of HIPK1 had a suppressive effect on the proliferation and EMT of LC cells." (PMID 34723781, 2021). "The results of xenografted tumor in nude mice manifested that miR-889-3p upregulation or HIPK1 knockdown clearly refrained from the volume and weight of subcutaneous tumor." (PMID 34723781, 2021). "In summary, the results suggest that miR-889-3p upregulation or HIPK1 knockdown represses tumor growth in vivo." (PMID 34723781, 2021). "The TUNEL assay on tumor revealed that miR-889-3p enhancement or HIPK1 repression apparently elevated the apoptosis rate of tumor tissue." (PMID 34723781, 2021). "The deletion of the miR-200c/141 cluster resulted in increased tumor metastasis and inhibited tumor growth by directly upregulating the target gene HIPK1." (PMID 33537063, 2020). "HIPK1 mRNA was enhanced in human LC tumor tissues and cells." (PMID 34723781, 2021). "In contrast, the direct upregulation of the target genes homeodomain-interacting protein kinase 1 (HIPK1) and the activation of β-catenin inhibit tumor growth." (PMID 39859424, 2025). "Clonal HIPK1 KO in SU_MB002 and HD-MB03 in vivo conferred a striking survival benefit and tumor burden." (PMID 36473869, 2022). "HIPK1 and HIPK3 had a lower expression in tumor tissues than that in corresponding non-cancerous normal tissues." (PMID 33495417, 2021).
cancer (6 papers, 2015 to 2022). A tumor composed of atypical neoplastic, often pleomorphic cells that invade other tissues. "RRA analysis further identify a set of MSI1-bound genes in G3 MB, including TMEM33, SFNX and HIPK1, as cancer-selective downstream targets for therapeutic drug targeting (i.e., not bound in NSC)." (PMID 36473869, 2022). "Human Hipk1 is also found at elevated levels in certain cancer cell lines and tissue samples." (PMID 29208636, 2018). "The development and clinical use of Wee1 and Hipk1 kinase chemical inhibitors might be a promising strategy to improve anti-cancer therapy." (PMID 27077811, 2016).
HIPK1 also shares sentences with these, for which no sentence is quoted: Cerebral ischemia (1 paper); hepatocellular carcinoma (1); hypertrophy (1); primary sclerosing cholangitis (1); rheumatoid arthritis (1); Rubinstein-Taybi syndrome (1); Sepsis (1); Splenomegaly (1); systemic lupus erythematosus (1); type 1 diabetes (1); type 2 diabetes (1); ulcerative colitis (1).